POLQ (DNA polymerase theta)
Diseases named in the same sentence as POLQ in open-access papers (continued):
Sharing a sentence is not in itself a finding about the gene and the disease.
tumor (continued). "In this regard, knockdown of POLQ increased the sensitivity of a panel of tumor cell lines from different primary sites to radiation in contrast to the normal tissue cells." (PMID 34201502, 2021). "First of all, the expression of POLQ in 50 normal tissues and 374 tumor tissues was collected from LIHC dataset of TCGA database." (PMID 34517891, 2021). "A common pattern of increased expression for POLE2 and POLQ in LUAD were found across thirty-seven tumor types." (PMID 31857847, 2019). "A pattern of increased expression typified by POLE2 and POLQ was found for multiple replication factors over thirty-seven tumor types." (PMID 31857847, 2019). "In the context of cancer, the up-regulation of POLQ is observed in different tumor tissues, including lung, stomach, colon, breast, melanoma and oral squamous cell carcinomas." (PMID 25409685, 2014). "We have recently demonstrated that tumour cells depleted of POLQ are rendered more sensitive to radiotherapy and that its limited expression in normal tissues made POLQ a potentially exploitable clinical target." (PMID 20700469, 2010). "We then correlated the level of POLQ expression with multiple pathological and demographic features such as patient age, tumour grade and tumour size." (PMID 20700469, 2010). "POLQ expression was normalised to the lowest level of tumour expression in the Affymetrix series, and to a panel of normal breast tissue samples for the Illumina series." (PMID 20700469, 2010). "It is notable that tumours that overexpress both POLQ and CCNE2 confer an extremely poor prognosis relative to the other groups (HR 3.26; 95% CI 1.88 to 5.66; p<0.001)." (PMID 20700469, 2010). "Inhibition of DNA polymerase theta (Polθ), an essential enzyme for repairing DNA double-strand breaks (DSBs) via microhomology-mediated end joining (MMEJ), has proven to be an exquisitely effective monotherapy in HR-deficient tumor models." (PMID 42284420, 2026). "Targeting the MMEJ pathway (e.g., via LIG3 inhibitors and POLQ inhibitors) could disrupt eccDNA biogenesis, potentially sensitising tumours to chemotherapy." (PMID 40984821, 2025). "Next, to determine whether POLQ regulation of DHODH was crucial for POLQ‐induced tumor stemness, we performed spheroid formation assay using a stable GC cell line knockdown POLQ and overexpressing DHODH." (PMID 38575587, 2024). "Thus, we display the potential of targeting POLQ, not only to achieve radiosensitization in radiation-naïve tumor cells but also to prevent or treat radio-recurrent disease." (PMID 39166898, 2024). "Furthermore, POLQ knockdown distinctly reduced the expression levels of MMP2 and MMP9, which were associated with tumor metastasis and invasion." (PMID 39520627, 2024). "POLQ inhibition in HR-deficient PDAC also results in more cytosolic micronuclei, activating the cGAS-STING signaling pathway, enhancing transcription of inflammatory cytokines, and increasing immune infiltration in the tumor." (PMID 36976649, 2023). "We, therefore, examined the potential efficacy of POLQ inhibition under DNA damage in SACC tumours." (PMID 35726713, 2022). "Consequently, POLQ is synthetic lethal with HR components and tumours compromised in HR repair are especially vulnerable to POLQ inhibition." (PMID 35774233, 2022). "Furthermore, genetic inactivation of POLQ is synthetic lethal with HR defects caused by either BRCA1, BRCA2, ATM, RAD51C or FANCD2 defects and tumour overexpression of POLQ correlates with HRD status and a poor clinical outcome." (PMID 35567571, 2022). "Furthermore, breast cancer related protein (BRCA) 2 and POLQ co-inhibition significantly improves tumor cell sensitivity to cisplatin." (PMID 35875060, 2022). "In basal-like tumor subtypes with BRCA-mutations, ZEB1 expression may occur late in the oncogenic process depending on high POLQ expression in order to survive with the HR deficiency." (PMID 34458275, 2021).
tumor (continued). "Furthermore, our work also proved the inhibition of tumorigenesis and tumor growth in vivo upon POLQ downregulation." (PMID 34517891, 2021). "POLQ was upregulated in 16 out of 25 of these ESCC tumor-normal pairs." (PMID 34206946, 2021). "We tested whether tumor mutation burden, patient outcome (disease-free survival) and immune cell infiltration measured by ESTIMATE can be attributed to mutations in POLQ and POLZ/REV3L." (PMID 32838755, 2020). "POLQ, which is prevalent in CRC, is regarded as a tumor promoter because its mutation could cause overexpression to promote cell migration." (PMID 32211020, 2020). "However, why mutations in POLQ and REV3L preferentially increase tumor mutation frequencies remains elusive." (PMID 32838755, 2020). "Disrupting either the DNA annealing factor RAD52 or the A-family DNA polymerase POLQ can cause synthetic lethality with defects in BRCA1 and BRCA2, which are tumor suppressors important for homology-directed repair of DNA double-strand breaks (DSBs), and protection of stalled replication forks." (PMID 31381562, 2019). "Similarly, POLQ gene expression in ovarian carcinoma shows that its expression correlates with tumor grade." (PMID 29301327, 2018). "This prompted us to speculate here that POLQ overexpression might give a selective advantage of growth/proliferation also to HR-proficient tumours." (PMID 27612511, 2016). "The large number of genes that overlap between these two groups may account for the clinical correlation between POLQ expression and high tumour grade." (PMID 20700469, 2010). "However POLQ is known to be overexpressed in a large proportion of tumours derived from patients with colon, lung, and gastric cancer." (PMID 20700469, 2010). "The correlation between POLQ expression and tumour grade and prognosis led us to assess whether genes that are co-expressed with POLQ are included in these validated gene expression signatures." (PMID 20700469, 2010). "In this current study we have demonstrated strong associations between POLQ expression and the presence of other individual factors such as tumour grade and ER negative disease that are known to confer an adverse prognosis." (PMID 20700469, 2010). "Furthermore, the expression of POLQ in ccRCC increased with tumor stage progression." (PMID 38270643, 2024). "Additionally, previous literature has reported that concurrent inhibition of POLQ expression during PARPi treatment of tumor cells exhibits a synergistic effect, resulting in the impairment of tumor cells' ability to preserve genomic integrity and subsequent cell death." (PMID 38270643, 2024). "In addition, the decrease in tumor growth with POLQ knockdown could be partly explained by antitumor immunity driven by CD8+ T cell influx." (PMID 36976649, 2023). "Hence, inhibition of POLQ exhibited synthetic lethality in HRD tumours." (PMID 37190285, 2023). "In addition, POLQ over‐expression dramatically decreased the size of SACC tumours." (PMID 35726713, 2022). "Thus POLQ could be considered as an important player in breast carcinogenesis, acting in this context as a tumor suppressor gene due to its important role in DNA repair." (PMID 25409685, 2014). "For the subcutaneous xenograft model, combined treatment with POLQ inhibitors and sulfasalazine, a ferroptosis inducer that inhibits SLC7A11, synergistically suppressed MGC-803 xenograft tumor growth." (PMID 38575587, 2024). "Nevertheless, we show that POLQ knockdown results in cGAS-STING activation and plays a complex role in the immune response that results in decreased tumor growth." (PMID 36976649, 2023).
tumor (continued). "Studies have shown that high expression of POLQ promotes CIN, such as genomic signal deletions and insertions and chromosome translocation, contributing to tumour progression." (PMID 35726713, 2022). "POLQ/FANCD2 single/double KO and control KYSE180TS/SLMT cells were injected into both flanks of the mice and the tumor volumes were measured weekly for 3 consecutive weeks." (PMID 34206946, 2021). "Since both POLQ and FANCD2 are DNA damage repair genes conferring tumor progression, we explored the possible synergistic or synthetic lethality relationships between POLQ and FANCD2 in ESCC tumorigenesis." (PMID 34206946, 2021). "Comparing polymerase components across thirty-seven tumor types revealed a common subset with elevated transcriptional pattern typified by POLE2 and POLQ that included EXO1, MCM10, GINS2, CDT1, ORC6L, and BLM." (PMID 31857847, 2019). "qPCR results revealed that the mRNA quantities of POLH, POLK, POLQ and REV3L in XP-V tumor cells were lower than those of the controls; however, the expression of POLI was higher in the XP-V tumor cells in the absence of UV irradiation (P<0.05)." (PMID 24260050, 2013). "Specifically, expression of POLK, POLQ and REV3L increased in the tumor cells while that of POLH, POLK, POLQ and REV3L decreased in the normal controls." (PMID 24260050, 2013). "We have also demonstrated that POLQ overexpression is associated with markedly increased rates of disease relapse, and using multivariate analysis, that these increased failure rates are independent of its association with features like tumour grade and ER status." (PMID 20700469, 2010). "Similarly, downregulation of POLQ gene expression enhances the activity of RAD51 protein‐mediated DNA repair pathways, thereby increasing tumor cell resistance to platinum‐based agents." (PMID 41473689, 2025). "Additionally, we found 50% of the tumour-matched SAPCS POLE, POLQ, and POLG carriers to present with an above median TMB." (PMID 41038821, 2025). "In COAD, we explored whether POLQ was involved in the Tumor immune microenvironment (TIME) by analyzing immune correlations between the high and low POLQ expression groups." (PMID 39520627, 2024). "Suppression of the POLQ, PRIM1 and RPA1 genes increased the radiosensitivity of tumour cells, while overexpression conferred increased resistance.Therefore, these genes could be potential therapeutic targets to improve the efficacy of radiotherapy." (PMID 39132508, 2024). "Moreover, the combination of POLQ inhibitor and ferroptosis inducer synergistically suppressed MGC-803 xenograft tumor growth and diminished metastasis." (PMID 38575587, 2024). "The level of POLQ expression was clearly different with age (P = 0.001) and gender (P = 0.017) but not with tumor size, histological type, differentiation, TNM stage, lymph node metastasis, depth of invasion, or venous invasion." (PMID 39520627, 2024). "Thus, we assessed how POLQ inhibition, with its observed effects on cGAS-STING signaling, influences the tumor immune response." (PMID 36976649, 2023). "Importantly, we show that the effects of POLQ in inducing microenvironmental change and tumor growth inhibition through STING signaling require an adaptive immune response, as these POLQ-mediated effects were lost in immunodeficient mice." (PMID 36976649, 2023). "A newly identified PolQ inhibitor Novobiocin resensitized these cancer cells to PARPi in vitro and in vivo by increasing the excessive DSB end resection and nonfunctional RAD51 foci-loading rates in HRD and PARP-inhibitor-resistant tumor cells." (PMID 36253861, 2022). "Indeed, in a backup DSB repair pathway (MMEJ), PolQ was found to be overexpressed in HRD and PARP-inhibitor-resistant tumor cells." (PMID 36253861, 2022). "Reduced POLQ expression inhibits DSB repair and tumor cell survival." (PMID 35875060, 2022).
tumor (continued). "It was firstly found in a Japanese study that POLQ was upregulated in tumor tissues, as compared with the paired non-tumor control samples in lung, colon and gastric malignancies." (PMID 34206946, 2021). "Depletion of POLQ (DNA polymerase theta) renders tumor cells more sensitive to radiotherapy without effecting normal tissues, providing ways to increase therapeutic window." (PMID 22228887, 2011). "We found that a significant number of tumours overexpressed POLQ and that overexpression was correlated with ER negative disease (p=0.047) and high tumour grade (p=0.004), both of which are associated with poor clinical outcomes." (PMID 20700469, 2010). "We found that POLQ overexpression correlated with both ER negative disease (p=0.047) and high tumour grade (p=0.004)." (PMID 20700469, 2010). "Its inhibition represents a synthetic lethal approach to blocking tumor growth while concurrently activating the cGAS-STING signaling pathway to enhance tumor immune infiltration, highlighting what we believe to be a new role for POLQ in the tumor immune environment." (PMID 36976649, 2023). "KPC-Brca2–/– shPOLQ tumors grew at a significantly slower rate and were much smaller compared with the KPC-Brca2–/– shCtrl group 28 days after implantation (tumor volume 213 ± 19 mm3 versus 633 ± 38 mm3, P < 0.001), while POLQ knockdown did not affect KPC tumor size." (PMID 36976649, 2023). "The clinical significance of tumour expression of POLQ has not previously been examined in detail." (PMID 20700469, 2010). "Based on these results, we concluded that the synthetic lethality by which POLQ and BRCA2 suppress tumor cells is a distinct mechanism independent of cGAS and STING." (PMID 36976649, 2023).
hematological cancer (1 paper, 2021). "We identified recurrent highly pathogenic variants affecting important drivers of hematological cancer (ATM), epigenetic regulators (ISX and SETDB1), and mediators of DNA replication (POLQ)." (PMID 33809641, 2021).
infection (1 paper, 2021). The state of being infected such as from the introduction of a foreign agent such as serum, vaccine, antigenic substance or organism. "After the infection of lentivirus plasmids prepared for silencing POLQ, the proliferation and migration of HCC cells were significantly inhibited and the cell apoptosis was dramatically increased." (PMID 34517891, 2021).
POLQ also shares sentences with these, for which no sentence is quoted: glioblastoma (3 papers); stomach cancer (3); oral squamous cell carcinoma (2); adenocarcinoma (1); blood cancers (1); cervical squamous cell carcinoma (1); chronic lymphocytic leukemia (1); cutaneous melanoma (1); endocervical adenocarcinoma (1); follicular lymphoma (1); Hereditary breast cancer (1); hypothyroidism (1); liver cancer (1); marginal zone lymphoma (1); non-Hodgkin lymphoma (1); ovarian serous cystadenocarcinoma (1); prostate adenocarcinoma (1); rectum adenocarcinoma (1); salivary gland tumours (1); sebaceous cancer (1); Sepsis (1); skin cancer (1); small-bowel cancer (1); thymoma (1); thyroid cancer (1).